CD44 (CD44 molecule (IN blood group))
Diseases named in the same sentence as CD44 in open-access papers (continued):
Sharing a sentence is not in itself a finding about the gene and the disease.
tumor (continued). "Studies showed that the CD44 variant (CD44v), a cell adhesion molecule widely expressed in various CSCs controls the intracellular levels of reduced GSH by directly interacting with the h SLC7A11, thereby promoting tumor growth." (PMID 35566360, 2022). "Furthermore, HA-coated PTX liposomes showed high accumulation in the tumor area because of a high level of CD44 in tumors, and promising results on antitumors have been achieved in 4T1 tumor-bearing mice." (PMID 35677298, 2022). "CD44-HA interactions are also responsible for progression towards gastric cancer after Helicobacter pylori infection whereby a cascade is triggered, which leads to degeneration of parietal cells followed by neoplasia." (PMID 34980167, 2022). "In 2009, Takaishi found that CD44+ cells could form globular colonies in serum-free medium, and xenograft tumours formed when they were injected into the subcutaneous and gastric walls of SCID mice." (PMID 36316684, 2022). "The transporters of ATP-binding cassettes might be bypassed by polysaccharide-based NPs, which are taken up by microfold cells or tumour cells that express CD44 in excess." (PMID 36559281, 2022). "It was confirmed that CD44 mRNA was highly expressed in tumour samples." (PMID 36316684, 2022). "The complex carbohydrates attached to the membrane proteins and extracellular matrix proteins, such as E-cadherin, integrins, Mucin1 (MUC1), and CD44, alter the structure and function of the glycoproteins, as well as intracellular signaling, to promote tumor metastasis." (PMID 35752750, 2022). "After adjusting for tumour purity, CD44 was significantly correlated with 38T-cell markers in STAD." (PMID 36316684, 2022). "Together, we identified CD44 as a negative regulator of heterotypic CIC formation on tumor cells." (PMID 35436988, 2022). "Furthermore, CD44 is one of the most commonly used cancer stem cell surface markers in sorting different subpopulations of tumor tissues." (PMID 36292918, 2022). "CD44 may become a useful prognostic biomarker by aiding in tumour grading and estimating CSC presence." (PMID 35842572, 2022). "Subsequent studies have found that only CD44+ cells can form gastric SCS-like tumours." (PMID 36316684, 2022). "Blocks simultaneously CD44 and EpCAM, reducing tumor progression and promoting apoptosis." (PMID 35785191, 2022). "The ectopic expression of TWIST1 in head and neck squamous cell carcinoma cells triggers EMT and leads to the acquisition of mesenchymal phenotypes of tumor cells, while the increased proportion of CD44-labeled cells in the tumor population can activate tumor initiation." (PMID 35637953, 2022). "The critical role for malignancy of stromal CD44 is further supported by a study that shows that mesenchymal stem cells require CD44 to be transformed into CAF in a conditioned media assay as well as in vivo recruitment to a tumor site." (PMID 36148042, 2022). "In addition, HA is the major extracellular matrix of tumor tissue and its receptor CD44 is highly expressed in many tumor tissues." (PMID 36324675, 2022). "It is also interesting to note that CD44 positive tumor cells are also captured by this technique." (PMID 35595733, 2022). "However, the role of the dynamic shift of CD44 in cancer cells collective detachment from primary tumor mass to circulation is poorly understood." (PMID 35680853, 2022). "Interestingly, miR-34a has been shown to directly inhibit tumor expression of the adhesion molecule CD44, which interacts with the extracellular matrix promoting migration and invasion of tumor cells, which is characteristic of metastatic behavior." (PMID 35214734, 2022). "For instance, P-selectin, a surface molecule on platelet membrane, can bind to CD44 expressed on the surface of tumor cells, and homotypic targeting enabled by cancer cell membrane coating is ascribed to surface markers such as Thomsen–Friedenreich antigen and E-cadherin." (PMID 35456631, 2022).
tumor (continued). "Among the molecules used to promote NP uptake, hyaluronic acid (HA) plays a major role for its tropism toward the cluster determinant 44 (CD-44), which is overexpressed in a wide array of malignant tumors, and is therefore attractive for the formulation of NPs for active tumor targeting." (PMID 36614044, 2022). "In particular, it allows an in situ tissue evaluation to distinguish the real tumor markers expression from a misleading stromal positivity (i.e. CD44 expression in the muscular wall of the bladder), thus, preventing potential overestimation of gene expression." (PMID 35805028, 2022). "Moreover, tumor-free mice exhibited a significant increase in proportion of CD44+CD62L− effector memory T cells in CD4+ and CD8+ T cell compartments compared with that in control mice." (PMID 35764365, 2022). "CSCs are the reservoir of cancer cells that exhibit surface markers such as ALDH, CD133 and CD44, possessing properties of self-renewal and the ability to reestablish the heterogeneous tumor cell population promoting metastatic colonization, self-renewal, and recurrence." (PMID 35800367, 2022). "A similar nanosystem (PheoA-SN38-HC) has been developed by Lee and co-workers, which contains the ROS-cleavable thioketal-SN38 for the drug release during PDT, showing good tumor targeting for CD44 positive cancer cells and effective tumor inhibition mediated by synergistic PDT-chemotherapy." (PMID 35890416, 2022). "To evaluate whether the CD44+CD133+ subpopulation of tumor-initiating Caco-2 cells was isolated successfully by FACS, we monitored these cells by flow cytometry analysis immediately after the primary sorting." (PMID 35433695, 2022). "On the other hand, the changeable dimeric conformation of CD44 affected by modification and membrane environments is related to the release of CTD to activate the downstream gene expression, which is implicated with tumor cell growth and proliferation." (PMID 35733341, 2022). "CD44 is a surface glycoprotein overexpressed in tumor cells." (PMID 35754803, 2022). "Even in PDAC, it has been found that the overexpression of CD44 could promote metastasis of tumor cells and reduce response to chemotherapy." (PMID 36358852, 2022). "Besides, a tumor formation experiment in nude mice revealed that the tumor volume (P < 0.05) and weight (P < 0.01) of CD44( +)BGC823/5-Fu inoculated mice were conspicuously larger than those of CD44(-)BGC823/5-Fu inoculated mice." (PMID 35941687, 2022). "Modulating the levels of CD44 at the cell surface in cancer cells, as well as interaction with hyaluronan, is thus of great importance for cancer therapy, to disrupt the signaling pathways that favor tumor progression and pathology spreading." (PMID 35328491, 2022). "The elevation of PKD1 and CD44 was particularly high in tumor cells close to the blood vessels." (PMID 36497140, 2022). "We took advantage of the cell membrane distribution of CD44 variants for aptamer discoveries and developed an HCC cell model (HKCI-C1) with both CD44E and CD44s over-expressed at a ratio mimicry in primary HCC tumor of 5:1." (PMID 34976591, 2022). "Moreover, the CD26 expression on NSCLC cells was associated with the expression of several antigens involved in the tumor suppression (such as the fibroblast-activating protein or the CD44 antigen), confirming its role as a tumor suppressor in this malignancy." (PMID 35205639, 2022). "CD44 chondroitin sulfate modification may be a target for inhibiting tumor cell motility and metastasis." (PMID 35936713, 2022). "The porous NPs could specifically target tumor cells through the binding of P-selectin to the CD44 and effectively release the Bu in the tumor region due to the acid condition." (PMID 36276066, 2022).
tumor (continued). "The study reported the presence of vimentin in detached and circulating tumor cells, suggesting acquisition of a cancer stem cell-like phenotype by these cells that co-expressed vimentin, CD44, and VE-cadherin at the periphery of tumor islands and invasive fronts." (PMID 35207438, 2022). "Through this interaction, CD44 potentially mediates tumor cell invasion." (PMID 35186752, 2022). "This leads to the conclusion that the prognostic value of CD44 depends not only on the total expression in tumour but also on tumour location and maybe even on subcellular location." (PMID 35296132, 2022). "Silencing CD44 indeed inhibited the coagulant properties of tumor cells which could contribute to the decreased ability of tumor cells to accomplish metastatic colonization when injected as CTCs in experimental metastasis assays." (PMID 35805061, 2022). "The level of CD44 cleavage is significantly associated with OPN and OPN–CD44 interaction, suggesting that both OPN and CD44 could be potential tumor markers for ATRT." (PMID 35954348, 2022). "When superimposing normal vs tumor tissues among each marker, only CD44 followed the same pattern in both tissues, with higher expression in patients over 65 years old, while the expression of CD166 and CD133 was completely opposite, each marker following the pattern of a mirror image." (PMID 36291969, 2022). "Collectively, these studies stipulated that presence of CD44 in a tumor tissues or cells might play a key role in treatment failure, lymph node metastasis, poor survival, and recurrence." (PMID 35274800, 2022). "High levels of CD44 (a transmembrane hyaluronic acid receptor) were associated with a significant decrease in median survival in tissue specimens from 62 GBM patients, and CD44 inhibition reduced tumor growth in a mouse model of GBM." (PMID 36276147, 2022). "There was a significant association between CD44+/CD24 low/− expression and the ability of the tumor to metastasize, as the expression of CD44+/CD24 low/− in patients with distant metastasis was 61% (range: 7–80%), compared to 25.3% (range: 0.1–68%) in those who had not metastasize (P = 0.038)." (PMID 36585652, 2022). "Our findings are indicative of (partial) epithelial–mesenchymal transition events giving rise to hybrid epithelial/mesenchymal and stem-cell-like tumor cell phenotypes in equine HNSCCs and suggest CD44 and CD271 as potential malignancy markers that merit to be further explored in the horse." (PMID 35215208, 2022). "Findings from various studies strongly support our hypothesis that the activation of CD44 by its major ligand hyaluronan (HA) activates the transcription of SOD2 to promote tumor cell invasion/metastasis." (PMID 35164076, 2022). "Human CD44/MYC-high cancer cells tended to localize the outside of the primary tumor." (PMID 35611554, 2022). "Further, we checked the percent of CD8 and CD44 cells in the tumor infiltrating lymphocytes." (PMID 36238311, 2022). "CD44 expression in tumours was compared with that in normal tissues at the same site." (PMID 36316684, 2022). "CD44 is a complex transmembrane-binding glycoprotein, which can be involved in the regulation of many important signaling pathways such as tumor proliferation, invasion, metastasis, and treatment resistance, and was related to the adverse prognosis of patients." (PMID 35330093, 2022). "Studies have also linked the MaSC hierarchy with the profile of tumor initiating cells/BCSCs characterized by CD44+/CD24- and ALDH+, where, CD44+/CD24- correspond to the MaSC population (EpCAMlow/-/CD49fhigh/+) and ALDH+ correspond to the luminal progenitor (EpCAMhigh/+/CD49fhigh/+) cells." (PMID 36157462, 2022). "Nanoparticles (NPs) coated with hyaluronic acid (HA) seem to be increasingly promising for targeted therapy due to HA chemical versatility, which allows them to bind drugs of different natures, and their affinity with the transmembrane receptor CD-44, overexpressed in tumor cells." (PMID 36614044, 2022).
tumor (continued). "Quantification of the colony formation assays for both groups showed that the number of colonies was significantly lower after KPT6566 treatment, indicating that KPT6566 might also be an effective inhibitor of CD44+CD133+ tumor-initiating Caco-2 cells." (PMID 35433695, 2022). "The tumor stemness biomarker CD44 was primary identification from WGCNA." (PMID 35941687, 2022). "Moreover, targetable signalling events observed in in vitro models of HNSCC were also connected with downregulation of Oct4, Sox2, nestin, and CD44 expression, as well as inhibited tumour sphere formation." (PMID 35276890, 2022). "CD44 is a cell-surface protein involved in cell adhesion, tumor invasion, and metastasis and its high expression is also recognized as a phenotypic marker for tumor-initiating cells (TICs)." (PMID 36077751, 2022). "Based on the observed inhibition of CD44/integrin α3/integrin α6/FAK in tumors with h4#147D treatment, h4#147D was considered to have caused cytoskeletal stress-mediated cell death in the tumor because these molecules are crucial for the organization of cytoskeletal proteins." (PMID 36385956, 2022). "The tumor and the stromal cells expressed CD44 and vimentin." (PMID 36415832, 2022). "HMSN–PA–HA could effectively accumulate at tumor sites by HA and CD44 interactions and release loaded drugs when hydrazine linkers between HA agents and HMSNs were broken, triggered by the low pH in the tumor microenvironment." (PMID 35845404, 2022). "Moreover, quercetin inhibited the tumor growth and metastasis formation of CD44+/CD24− CSCs and reduced the expression levels of ALDH1A and CXCR4." (PMID 36498571, 2022). "CD44 induces upregulation of genes that are involved in tumor modulation." (PMID 36185622, 2022). "The difference in CD44 expression between the tumor body and tumor buds was significant (P <0.001)." (PMID 35860042, 2022). "Moreover, Hendawy also found markedly higher CD44 expression in tumours of bigger size, overall higher TNM stage, lymphovascular invasion, and metastasis." (PMID 35296132, 2022). "Furthermore, hyaluronic acid that is shed by tumor cells in the MVN-chip model assists the adhesion of cancer cells to the endothelium via interaction with glycoprotein CD44." (PMID 35158914, 2022). "Indeed, the enrichment of TNBC tumours with CD44+/CD24− cells confers them to a higher proliferation, migration, invasion, and tumorigenic capacity." (PMID 36077812, 2022). "In addition, TGF-β, JAK/STAT, and IL-6/STAT3 signaling pathways contributed prominently to the stemness regulation of CD44+ cells, resulting in their vital roles in tumor initiation and growth." (PMID 36293184, 2022). "CD44 is a transmembrane glycoprotein that is overexpressed on the surface of many tumor cells." (PMID 35953863, 2022). "A colony formation assay of both subpopulations showed that the number of colonies was significantly lower after Juglone treatment, indicating that Juglone might be an effective inhibitor of CD44+CD133+ tumor-initiating Caco-2 cell-mediated tumorigenesis." (PMID 35433695, 2022). "Flow cytometry results are in line with confocal microscopy results, supporting that the cellular uptake of Epi-Nio-HA nanoparticles is based on CD44-mediated endocytosis mechanism, which leads to a larger number of nanoparticles internalized into CD44-overexpressing tumor cells." (PMID 35875198, 2022). "Using zebrafish model, we show that HA-CPNs cause selective growth inhibition of the CD44 + but not CD44- tumour foci over time, either in individual xenografts or using CD44 + /CD44- co-injection model." (PMID 35840697, 2022). "Several tumor cell surface markers are identified as specific and selective targets for anticancer therapy and present promising results as targeting agents in nanosystems such as CD44, CD147, CD133, and CD321." (PMID 35456655, 2022).
tumor (continued). "They prevent the association of MMP9 with its receptors (α4β1 integrin/CD44), resulting in the blocking of a downstream signalling pathway required for MMP9-mediated tumour cell migration in vitro and the inhibition of tumour metastasis in xenograft mouse models of lung cancer." (PMID 35158891, 2022). "As a negative regulator of CD44 expression, miR-34a is frequently under-expressed in tumor tissue." (PMID 36182897, 2022). "Despite Annexin A2, CD44 is also present on the surface of exosomes in GBM that plays as a receptor for hyaluronic acid and it is implicated that CD44 is a marker for cell motility, tumor growth, angiogenesis, and cancer stem cell." (PMID 35371984, 2022). "Thus, targeting Pin1 in CD44+CD133+ tumor-initiating cells is a promising therapeutic approach to treating human CRC." (PMID 35433695, 2022). "The observed lower increase in CD44 expression in fibroblasts after treatment with exosomes from drug-treated tumor cells could potentially indicate a reduction in metastatic activity." (PMID 36012171, 2022). "qRT-PCR analysis revealed that CD44 is expressed in both tumor and peritumor mucosa." (PMID 36291969, 2022). "Immune infiltration and immune checkpoints suggest that in cluster 1 there is an increased number of highly infiltrated CD86 and LAG3 cells, which are more active in boosting inflammation, and that CD44 has a higher activity and is more able to promote tumor metastasis." (PMID 36186475, 2022). "In addition, as a biomarker of gastric cancer stem cells (GCSCs), CD44 is involved in tumor growth and maintenance of cancer cell stemness." (PMID 35669102, 2022). "Interestingly, an abundance of CD44+/CD24− cells has been reported in TNBC tumours compared with luminal and HER2 subtypes." (PMID 36077812, 2022). "Of particular note, CD44 is also identified as a cancer stemness marker in a number of cancer types including OSCC, and the expression level of CD44 has been found to be positively associated with tumor development and progression." (PMID 35629265, 2022). "Interestingly, CD44 was one of the first identified cancer stem cell markers, indicative for tumor self‐regeneration after transplantation into immune‐deficient mice." (PMID 34951143, 2022). "Furthermore, primary tumour cells (FaDu) contained 63.8% cells with CD44-negative status and only 36.1% cells with CD44+ status, 95.5% of metastatic Detroit 562 cells showed CD44+ status." (PMID 35565415, 2022). "Notably, MEX3A inhibition not only suppresses proliferative capacity of tumor cells, but also renders tumor cell-state conversion from stemness to differentiation, evidenced by reduction of CD44 and upregulation of E-cadherin." (PMID 36276637, 2022). "Systemic distribution of miR-34a in carriers of liposomes resulted in lower growth of the tumor, enhanced tumor cell death, and reduced CD44+ cell numbers in a model of orthotopic pancreatic cancer employing cells of MiaPaca2, depicting a reduction in metastatic cells." (PMID 36071981, 2022). "However up to date, little is known of the role of CD44 on cells from the tumor microenvironment (TME)." (PMID 35992852, 2022). "In addition, polysaccharide-based biomaterials HA and CS have attracted great interest as tumor drug delivery systems due to their good biocompatibility with and targeting to CD44." (PMID 35936713, 2022). "Interestingly, injection of GL261 cells revealed a trend towards an even higher tumor volume in CD44 cKO mice two weeks post-injection." (PMID 35992852, 2022). "Hence, our findings demonstrate that miR-34a is a PCSC suppressor that inhibits tumor development and metastasis by directly targeting CD44." (PMID 36139695, 2022). "Notably, CD44-targeted NIR-PIT combined with CTLA4 or PD-1/PD-L1 blockade showed varying antitumor responses in different tumor models." (PMID 36276636, 2022). "CD44 has been considered a CSC marker in several tumor types." (PMID 35011702, 2022). "This fact was kept in mind when assessing the numbers of CD44+ tumor cells." (PMID 35215208, 2022).